CD274 (CD274 molecule)
Diseases named in the same sentence as CD274 in open-access papers (continued):
Sharing a sentence is not in itself a finding about the gene and the disease.
breast tumor (184 papers, 2008 to 2026). "The expression of CD274 was investigated in the transcriptome of breast tumors according to clinical-associated data of the TCGA invasive breast cohort." (PMID 38201582, 2023). "In breast tumors from the TCGA cohort, the expression of CD274 is associated with overall survival, and tumors presenting high expression levels of CD274 upregulated some ferroptosis-driver genes also associated with prognosis, like IDO1, IFNG and TNFAIP3." (PMID 38201582, 2023). "Breast tumors presenting high expression of CD274 upregulated some ferroptosis drivers associated with prognosis: IDO1, IFNG and TNFAIP3." (PMID 38201582, 2023). "In breast tumor, we observed that breast tumors, which harbored high levels of CD274, upregulated the expression of ferroptosis-driver genes." (PMID 38201582, 2023). "Immunohistochemistry was used to evaluate VEGFA and MIF levels in breast tumors and normal breast tissues; qPCRs and western blots were used to validate the expression of clinical immuno-oncology (IO) therapeutic targets CD274 (PD-L1) and IL8 in cell lines." (PMID 31293831, 2019). "The expression level of CD274 mRNA is also the highest in ER−/HER2− breast tumors." (PMID 38893094, 2024). "The expression of CD274, IFNG, TNFAIP3 and IDO1 was investigated in an independent cohort of the transcriptome: METABRIC cohort comprising 1866 breast tumors." (PMID 38201582, 2023). "In addition to IDO1, PD-L1 (CD274) was also upregulated in placenta and breast tumor as compared to uterus and normal breast tissue." (PMID 27852037, 2016). "In the breast tumor transcriptome from the TCGA cohort, univariate overall survival analyses according to the expression of ferroptosis drivers highlighted a significant favorable expression for three of them: IFNG, IDO1 and TNFAIP3 conjointly with CD274 expression (univariate Cox p-value = 0.08)." (PMID 38201582, 2023).
endometrial cancer (184 papers, 2014 to 2026). Primary or metastatic malignant neoplasm involving the endometrium (mucous membrane that lines the endometrial cavity). "The overexpression rates of PD-1 (CD279) and PD-L1 (CD274) in endometrial cancer have been reported to be the highest of all gynaecological cancers, so we evaluated LAMP3 expression levels and the correlation of multiple immune checkpoints in detail." (PMID 38217544, 2024). "First, we included the expression profile data of all normal endometrial samples and endometrial cancer samples of TCGA and observed the expression levels of common immune checkpoints, including PDCD1, CD274 (PDL1), PDCD1LG2 (PDL2), CTLA4, LAG3, and HAVCR2." (PMID 37872211, 2023).
esophageal squamous cell carcinoma (176 papers, 2016 to 2026). Esophageal squamous cell carcinoma (ESCC) is a type of esophageal carcinoma (EC) that can affect any part of the esophagus, but is usually located in the upper or middle third. "In this study, we investigated PSD3, CD274 (PD-L1), and TNFSF18 as potential immune-related biomarkers in esophageal squamous cell carcinoma (ESCC) using integrative transcriptomic and experimental approaches." (PMID 40895529, 2025). "In this study, we selected PSD3, CD274, and TNFSF18 for integrated analysis based on a combination of transcriptomic screening, immunological relevance, and prognostic associations in esophageal squamous cell carcinoma (ESCC)." (PMID 40895529, 2025).
colitis (170 papers, 2016 to 2026). Inflammation of the colon. "The CD274 (PD-L1) is widely known for its key role in the immunosuppressive tumor microenvironment and is a target for cancer therapies (together with PD-L1 receptor, PD-1), which can cause colitis through the activation of resident memory CD8+ T cells." (PMID 36140740, 2022). "However, while they served to prevent excessive tissue damage in colitis, in models of lung inflammation, CD274-positive eosinophils promoted inflammation." (PMID 41050650, 2025).
COVID-19 (162 papers, 2020 to 2026). A disease caused by infection with severe acute respiratory syndrome coronavirus 2. "CD274 (PD-L1) expression increases in severe COVID-19 patients and is associated with cytokine storm and CD8+ T cell exhaustion." (PMID 38440722, 2024). "Cd274+ and Cst7+ neutrophils were previously observed in the blood sample of COVID-19 patients and associated with disease severity, confirming the clinical relevance of our finding and indicating the importance of this group of neutrophils in understanding COVID-19." (PMID 39414783, 2024). "CD274 (PD-L1), which has been implicated in dysregulated neutrophil responses in severe COVID-19, and PADI2, an enzyme involved in the citrullination of arginine residues and neutrophil extracellular trap (NET) formation, were also highly expressed in the TV group compared to the other two groups." (PMID 37026002, 2023). "A study of dysregulated myeloid cell responses in COVID-19 revealed that presence of CD274 and ARG1 expressing dysfunctional mature neutrophils contributed to severe COVID-19 disease." (PMID 37026002, 2023). "It has been demonstrated that neutrophils from severe COVID-19 patients were persistently increased in PD-L1 (CD274) expression compared to those from healthy controls by single-cell transcriptomes and proteomics." (PMID 36159873, 2022). "To gain further insight in COVID-19-induced immunesuppression, we profiled monocyte expression of PD-L1 (CD274), ARG1, and HLA-DR by flow cytometry." (PMID 33674591, 2021). "While all LDN expressed high levels of S100A8 and S100A9, alarmins described to have predictive functions for COVID-19 severity, CD274 (PD-L1) and ARG1 were also expressed in distinct LDN subsets." (PMID 33841435, 2021). "The heightened expression of CXCR4 and CD274 (PD-L1) in LDNs indicates a potential mechanism for immune evasion and persistent inflammation, adding a new dimension to the understanding of neutrophil heterogeneity in COVID-19." (PMID 39928675, 2025). "Finally, CD274 (PD-L1), a known inhibitor of T cell activation, was highly expressed in COVID-19(+) TV skin tissue compared to the other 2 groups." (PMID 37026002, 2023). "In addition, we found other cell-death-associated proteins (CD274, HTATIP2, and S100A8) in the patients, which supports the observation that severely diseased COVID-19 patients develop thrombocytopenia." (PMID 37681923, 2023). "In comparison to the COVID-19(-) PU controls, genes highly expressed in the TV group fell into categories that included neutrophil dysfunction (CD274, PADI2), inhibition of B and T cell responses (CD22, IRF4, ORAI1), and upregulation of pro-inflammatory response pathways (CARD8, MAPK7, IRF7, IFIH1)." (PMID 37026002, 2023). "Moreover, we observed increased expression of CD274/PD-L1, which may further contribute to reduced T cell function in severe COVID-19." (PMID 37365222, 2023). "Immuno-phenotyping studies have revealed that programmed death receptor ligand 1 (PD-L1, CD274, B7-H1; family of B7 costimulatory molecule) is dysregulated on monocytes, neutrophils, and T cells in COVID-19 patients." (PMID 35280992, 2022). "As for immunosuppressive properties, PD-L1 (CD274) is up-regulated and dysregulated in several types of immune cells of COVID-19 patients’ monocytes, neutrophils, gamma delta T cells, and CD4+ T cells." (PMID 36159873, 2022). "SPP1 protein is expressed by COVID-19 BALF macrophages, drives proinflammatory activation of classical monocytes, and the differentiation of neutrophils toward a proinflammatory CD274+ (PD-L1+) phenotype." (PMID 34143756, 2021). "We decided to measure CD274 as the exhaustion of CD8 + T cells with the elevation of PD-1 (programmed cell death protein 1, also known as CD279) expression is present in severe COVID-19 patients." (PMID 34045585, 2021).
COVID-19 (continued). "In line with the single-cell study, signs of an interferon response were observed irrespective of disease severity (IFIT1, IFIT3), while only severe COVID-19 patients’ granulocytes featured expression of genes with suppressive functionality, such as ARG1 or CD274 (PD-L1)." (PMID 33441124, 2021). "We also found that CD274 expression was elevated in A549 cells treated with SARS-CoV-2 virus compared to mock-treated cells and in virus infected lung cells of COVID-19 patients." (PMID 34045585, 2021). "Herein, we spotted CD58, a nonclassical monocyte, such as CD274 (PD-L1) known inhibitor of T-cell activation along with Arginase 1 highly expressed in neutrophils in COVID-19 patients or CD24 involved in neutrophil degranulation with an increased expression of neutrophil function." (PMID 36806094, 2023). "When these significant outcomes were adjusted for sex and age, only the frequency of NK cells (p-adjusted = 0.04), the MFI of CD274 on monocytes (p-adjusted = 0.03) and the MFI of TREM-1+ on HD neutrophils (p-adjusted = 0.03) remained significantly increased in OB patients with severe COVID-19." (PMID 37626613, 2023). "Interestingly, macrophages from severe COVID-19 patients expressed higher levels of CD274 (PD-L1) yet the expression of PDCD1LG2 (PD-L2) was not significantly different between moderate and severe patients." (PMID 33178221, 2020).
oral squamous cell carcinoma (148 papers, 2015 to 2026). "A possible role for the AhR in this important pathway was suggested by our previous studies showing that the AhR regulates CD274/PD-L1 expression in oral squamous cell carcinomas." (PMID 40449595, 2025). "A report in oral squamous cell carcinoma showed that CD274-amplified tumors has a significantly higher frequency of positive PD-L1 staining than cases without amplification." (PMID 31500314, 2019).
diabetes (145 papers, 2012 to 2026). "CD274 may become an immunotherapy target in diabetes-related cardiovascular complications." (PMID 36158806, 2022). "This study aims to investigate the effects of hyperglycemia on the gene and protein expression of CD36, CD69, CD274, and TLR-7 during wound healing using a rat model of induced diabetes." (PMID 41465460, 2025).
leukemia (143 papers, 2011 to 2026). A malignant (clonal) hematologic disorder, involving hematopoietic stem cells and characterized by the presence of primitive or atypical myeloid or lymphoid cells in the bone marrow and the blood. "Co-expression of the CD274 gene, encoding PD-L1, and mCherry fluorescent protein was achieved in human leukemia K562 cells by lentiviral transduction." (PMID 33653969, 2021). "As copy number, as well as transcriptional regulation of the CD274 gene may be altered in cancer cell lines, particularly in leukaemias, we next investigated variant 1 and CD274-L2A expression in healthy immune cells." (PMID 31729316, 2019). "Out of 17 genes that mapped to the DISEASE database, 7 have been linked to pathogenesis of human CLL and/or other leukemias (Birc3, Wnt5a, SP140, Atr, Lyn, CD274, and Flt3), and SIFT analysis revealed that the detected mutation in Lyn is likely deleterious." (PMID 34417556, 2022). "Our findings shed new light on the treatment for leukemia by targeting certain surface immune molecules of LICs, such as CD274." (PMID 27855694, 2016). "The histological hematoxylin/eosin staining also revealed that there were much less infiltrated leukemia cells in the spleen of the mice transplanted with CD274-null leukemia cells." (PMID 27855694, 2016). "Consistently, we also found that the values of the size and weight of the spleen of the recipients that received primary CD274-null leukemia cells were lower than those of the WT controls." (PMID 27855694, 2016). "More strikingly, the recipients transplanted with 2000 CD274-null leukemia cells had significantly prolonged survival compared to that of their WT counterparts (p < 0.05)." (PMID 27855694, 2016). "The survival of the mice with CD274-null leukemia cells was dramatically extended during the serial transplantation compared with that of their WT counterparts." (PMID 27855694, 2016). "Moreover, CD274 was directly associated with JNK and enhanced the downstream signaling to increase the Cyclin D2 level, promoting leukemia development." (PMID 27855694, 2016). "However, the role of CD274 in leukemia-initiating cells (LICs) remains largely unknown." (PMID 27855694, 2016). "We also provided intriguing evidence showing that CD274 directly interplays with JNK and enhances its activities to upregulate Cyclin D2 level, leading to the acceleration of leukemia development." (PMID 27855694, 2016). "The CD274/JNK/Cyclin D2 pathway promotes the cell cycle entry of LICs, which may serve as a novel therapeutic target for the treatment of leukemia." (PMID 27855694, 2016). "Then, we further examined the lineages of CD274-null leukemia cells and found that the differentiation status was not altered according to the analysis with the surface markers of Mac-1 and Gr-1 (Mac-1+/Gr-1+ cells representing a more mature leukemia cell population)." (PMID 27855694, 2016). "Our results highlight that CD274/JNK/Cyclin D2 signaling controls the cell cycle entry of LICs and leukemia development, which may be helpful for the further identification and understanding of the role of other novel surface immune molecules in the maintenance of LIC pool." (PMID 27855694, 2016).
renal carcinoma (142 papers, 2015 to 2026). A carcinoma arising from the epithelium of the renal parenchyma or the renal pelvis. "PD-L1, the product of the CD274 gene, is an immune checkpoint protein highly expressed in renal carcinoma." (PMID 34736454, 2021).
B-cell lymphoma (120 papers, 2011 to 2025). "Remarkably, CD274 mutations and deletions are significantly associated with a loss of function mutations of TNFRSF14 in this low grade B-cell lymphoma, which typically arises from a background of autoimmune Hashimoto’s thyroiditis." (PMID 34021249, 2021). "In a Myc-driven B cell lymphoma, the BETi JQ1 inhibits the PD-1/PD-L1 axis by the loss of CD274 (PD-L1) mRNA production." (PMID 32708698, 2020). "The co-inhibitory molecule programmed cell death 1 ligand 1 (PD-L1, CD274) plays important roles in the development of many types of malignancies, including B-cell lymphoma." (PMID 36765793, 2023). "As an example of MYC-independent targeting, genome-wide analysis of JQ1-induced transcriptional response in MYC-driven B-cell lymphoma revealed reduced BRD4 occupancy at the IFNγ PD-L1 ligand Cd274 without affecting MYC occupancy, resulting in a reduction of the CD274 mRNA level." (PMID 30906568, 2019).
lung squamous cell carcinoma (120 papers, 2015 to 2025). "In conjunction with the survival curves drawn using TCGA data of lung squamous cell carcinoma, we analyzed the median recurrence-free survival (mRFS) and median OS (mOS) of patients according to high or low expression levels of PD-L1 (CD274) and PVR." (PMID 33879814, 2021). "In lung squamous cell carcinoma, 38 genes were identified for CTLA4, 20 genes for CD274 expression." (PMID 27683114, 2016).
pancreatic ductal adenocarcinoma (118 papers, 2016 to 2026). An infiltrating adenocarcinoma that arises from the epithelial cells of the pancreas. "For instance, AK104 (PD-1+CTLA4) has been approved for platinum-refractory or metastatic cervical cancer, and KN046 (CD274+CTLA4) has entered Phase III clinical trials for pancreatic ductal adenocarcinoma (PDAC) and NSCLC." (PMID 38713378, 2024).
acute myeloid leukemia (117 papers, 2012 to 2026). Acute myeloid leukemia (AML) is a group of neoplasms arising from precursor cells committed to the myeloid cell-line differentiation. "Similarly, the results of other investigations also revealed that the overall survival of acute myeloid leukemia mice was dramatically extended upon the treatment with anti-CD274 monoclonal antibodies." (PMID 27855694, 2016). "In a model of acute myeloid leukemia, the expression by cancer cells of the immune checkpoints CD274 (best known as PD-L1) and CD80 (also known as B7.1) prevented T cell activity and preserved cancer dormancy." (PMID 33193295, 2020). "We established an MLL-AF9-induced acute myeloid leukemia (AML) model with wild-type (WT) and CD274-null mice to elucidate the role of CD274 in the cell fates of LICs, including self-renewal, differentiation, cell cycle, and apoptosis." (PMID 27855694, 2016). "Additionally, we looked at the age-related changes in CD274 expression in patients suffering from each tumor type and discovered that older individuals had higher levels of expression in COAD, HNSC, LAML (acute myeloid leukemia), LGG, and UCS." (PMID 38166842, 2024).
myocarditis (111 papers, 2015 to 2026). Myocarditis is a condition that is characterized by inflammation of the heart muscle (myocardium). "Based on the transcriptional profile and surface assessment of CD274 and CD101, our data show that eosinophils in the heart of hypereosinophilia-associated myocarditis are type 1 polarized." (PMID 41050650, 2025). "Previous studies have shown that the inhibition of PD-L1 (CD274) signaling to treat cancer leads to subsequent myocarditis in humans, which can be alleviated with immunosuppression." (PMID 38012001, 2024).
kidney cancer (102 papers, 2015 to 2025). Primary or metastatic malignant neoplasm involving the kidney. "Intriguingly, kidney cancer cell lines with wild-type TUBA1C displayed a higher CD274 dependency score than their mutant counterparts." (PMID 39301023, 2024). "Kidney cancer is a highly immunogenic tumor in which the tumor cells produce an immunosuppressive environment through a variety of mechanisms, such as increased expression of immunosuppressive molecules(PDCD1, CD274, CTLA4) in the TME and the occurrence of immune escape." (PMID 35860566, 2022).
clear cell renal cell carcinoma (101 papers, 2010 to 2026). "We hypothesized that single nucleotide polymorphisms (SNPs) in the PDCD1 and CD274 genes, encoding PD-1 and PD-L1, are associated with clinicopathological features, PD-L1 immunohistochemical expression, and clinical outcomes in clear cell renal cell carcinoma (ccRCC)." (PMID 42074079, 2026). "In parallel, DLAT expression was also found to be positively correlated with immune B cell infiltration and CD274 expression in clear cell renal cell carcinoma." (PMID 36203594, 2022).
thyroid cancer (101 papers, 2014 to 2026). "We first assessed the prognostic relationship between PDCD1 and CD274 in patients with thyroid cancer." (PMID 34376710, 2021). "Our group and others have shown that BRAFV600E-mutant thyroid cancers have increased expression of Programmed Death Ligand 1 (PD-L1, CD274), a physiologic “checkpoint” expressed on tumour cells, macrophages, and other cell types." (PMID 30327563, 2018). "Then we explored the correlation between PDCD1 and CD274 and immune cells in thyroid cancer." (PMID 34376710, 2021).